BRAF (B-Raf proto-oncogene, serine/threonine kinase)
Diseases named in the same sentence as BRAF in open-access papers (continued):
Sharing a sentence is not in itself a finding about the gene and the disease.
melanoma (continued). "This dataset compares 4 drug-tolerant states (neural crest stem cell, invasive, “starved-like” melanoma cell, and pigmented) that are present in MRD following BRAFi + MEKi in BRAF-mutant melanoma patient–derived xenografts (PDXs)." (PMID 40955663, 2025). "Significant progress in the treatment of melanoma has been made following the introduction of immune-checkpoint inhibitors and targeted therapies (especially BRAF and MEK inhibitors)." (PMID 41373567, 2025). "The integration of ICIs, such as PD-1/PD-L1 inhibitors, with BRAF/MEK inhibitors represents a transformative approach in melanoma treatment." (PMID 39897423, 2025). "Our results suggest that targeting NR2F1 in concert with BRAFi + MEKi will likely promote more durable responses to targeted therapy for BRAF-mutant melanoma in vivo." (PMID 40955663, 2025). "In BRAF-mutant melanomas, Wnt5a overexpression drives stromal fibrosis and DC tolerization, creating an immune-excluded TME." (PMID 40861441, 2025). "These mutations represent a critical therapeutic target, as evidenced by the transformative impact of BRAF inhibitors in melanoma and other cancers." (PMID 41282105, 2025). "The introduction of immune checkpoint inhibitors and targeted therapies, such as BRAF/MEK inhibitors for BRAF-mutant melanoma, has greatly improved survival rates, including progression-free and overall survival." (PMID 41019059, 2025). "Targeted therapy for malignant melanoma with BRAF inhibitor (BRAFi) or its combination with MEK inhibitor (MEKi) improves the clinical outcomes of patients, but resistance develops invariably." (PMID 40745979, 2025). "BRAF/MEK inhibitors target a key proliferative pathway in melanoma, offering clinical benefit but limited durability." (PMID 40564107, 2025). "Although targeted therapies initially show high efficacy in BRAF-mutant melanoma, they frequently develop resistance due to metabolic rewiring." (PMID 40573249, 2025). "In this study, BRAF + MEK blockade was superior to second‐line adjuvant PD‐1 treatment in BRAF(V600E) mutant melanoma (HR 0.192 (0.05–0.731), p = 0.016)." (PMID 40331873, 2025). "GSK3β expression and activation in A375 BRAF-V600E mutant melanoma cells were assessed prior to BRAFi treatment, in BRAFi-sensitive cells and after developing BRAFi resistance at RNA and protein levels." (PMID 40184329, 2025). "Melanoma is aggressive and often metastasizes, commonly driven by NRAS and BRAF-V600E mutations that activate MAPK and PI3K pathways." (PMID 41527622, 2025). "Dermoscopically, shiny white structures (OR = 3.50; 95% confidence interval: 1.13–10.84) were associated with BRAF-mutated melanomas, whereas a homogeneous disorganized pattern was associated with NRAS-mutated melanomas (OR = 6.96; 1.49–32.53)." (PMID 40867317, 2025). "In the case of mutant BRAF inhibitors in melanoma, the acquired resistance is conferred by mechanisms involving genetic and epigenetic changes that activate different signaling pathways such as MAPK to bypass the effect of BRAF inhibition." (PMID 40649216, 2025). "Low MITF expression has been associated with resistance to immune checkpoint inhibitors, particularly in melanoma treated with BRAF/MEK inhibitors." (PMID 39976551, 2025). "BRAF and MEK proteins activate the MAPK pathway, driving proliferation and survival, particularly in cancers harboring BRAF V600E mutations, such as melanoma." (PMID 40872476, 2025). "SIRT1 inhibition by sirtinol or EX-527 re-sensitized resistant BRAF-mutant melanoma cells to vemurafenib, and it was shown that SIRT1 downregulation promotes senescence, while upregulation promotes proliferation." (PMID 39935431, 2025). "Mutations in the BRAF gene are common in CM, and patients with BRAF-mutant melanoma often respond well to combined inhibition of BRAF and MEK (BRAFi + MEKi)." (PMID 40955667, 2025).
melanoma (continued). "A key molecular feature of melanoma is the frequent occurrence of activating mutations in the MAPK pathway, particularly in BRAF (most commonly the oncogenic BRAFV600E mutation), which has been successfully targeted with inhibitors such as vemurafenib." (PMID 41063628, 2025). "The resistance of BRAF and NRAS mutated melanoma cells to the MEK inhibitor selumetinib is also associated with the increased level of OXHPOS activity." (PMID 40612109, 2025). "The aim of the present study was to identify factors predictive for long-term versus short-term survival of a real-world cohort of stage IV melanoma patients after onset of a modern first-line therapy with PD-1-based ICI or BRAF/MEK-directed TT." (PMID 40028330, 2025). "Given the frequency of aberrant MAPK/ERK activity observed in melanoma, several inhibitors have been developed to target components of this pathway, including inhibitors of BRAF, MEK and more recently RAS and ERK." (PMID 40058234, 2025). "Combination therapies involving BRAF and MEK inhibitors have become the standard of care for advanced melanoma with BRAF mutations." (PMID 40063190, 2025). "Its loss leads to pathway hyperactivation, allowing melanoma cells to bypass MAPK inhibition, even under BRAF or MEK-targeted therapy." (PMID 40332392, 2025). "Three patients with advanced BRAF+MEK inhibitor-resistant melanoma, who suffered from progression upon dabrafenib plus trametinib therapy, were treated with vorinostat (360 mg/day, orally), which suppressed SLC7A11 in taken biopsies." (PMID 39935431, 2025). "Despite these data, the use of immunotherapy in a patient with BRAF wild-type melanoma and, more specifically, the use of combined CTLA-4 and PD-1 checkpoint-inhibition therapy with recurrent resectable melanoma is a rational therapeutic choice." (PMID 39940799, 2025). "Early-phase clinical trials, initiated in 2008, confirmed the preclinical evidence, showing substantial tumor regression and ORRs ranging from 50% to 80% in patients with advanced BRAF-mutant melanoma." (PMID 41302945, 2025). "The development of vemurafenib, a BRAF inhibitor, was guided by these canine studies and has become a cornerstone therapy for BRAF-mutant cancers, including bladder and melanoma in humans." (PMID 39943159, 2025). "Another study found that in BRAF-mutant melanoma, cytoprotective autophagy plays a key role in the development of resistance to BRAF inhibition." (PMID 40248706, 2025). "Previously, Haq and colleagues demonstrated that BCL2A1 is a melanoma-specific oncogene and likely plays a key role in the development of resistance to BRAF inhibitors." (PMID 41465443, 2025). "ROCK inhibitors also overcome targeted therapy resistance: Y-27632, GSK269962A, or fasudil restore BRAF inhibitor efficacy in melanoma, and ROCK1 silencing sensitizes BRAF/NRAS-mutant cells to MAPK inhibitors." (PMID 40368918, 2025). "Using PLX4032-resistant cell sublines, artificially derived from BRAF V600E-positive melanoma cell lines, key findings were validated in PLX4032-resistant tumors and in short-term cultures derived from patients involved in clinical trials." (PMID 40872623, 2025). "Functional validations confirm that AKT2-206 confers BRAF inhibitor resistance in melanoma cells by activating S6 kinase." (PMID 40681872, 2025). "We recently found that upregulation of DBL family guanine exchange factors (GEFs), such as Vav1, can promote BRAFi/MEKi resistance in BRAF V600-mutant melanoma cells." (PMID 41109929, 2025). "Future studies, besides a larger cohort of patients, will include various treatment protocols with the combined targeting of different immune checkpoints or BRAF and MEK inhibitors, associated with clinical evidence for melanoma patients." (PMID 40564098, 2025). "ER-mediated protective autophagy represents another critical resistance mechanism in BRAF-mutant melanoma." (PMID 40655947, 2025).
melanoma (continued). "An example is given by BRAF-mutant melanoma, where ERK1/2 is considered to be the key oncogenic driver." (PMID 40723336, 2025). "In both melanoma and papillary thyroid cancer, however, expression of BRAF did correlate with MAPK activation as reflected by the MPAS." (PMID 40869231, 2025). "For example, in melanoma, combination nivolumab/ipilimumab followed by BRAF and MEK inhibitor therapy is the recommended treatment sequence, whereas in early stage NSCLC, atezolizumab is indicated following adjuvant platinum-based chemotherapy." (PMID 40227779, 2025). "Structural biology has revolutionized drug discovery, enabling the development of targeted therapies such as vemurafenib for BRAF-mutant melanoma and nirmatrelvir for COVID-19." (PMID 41209584, 2025). "CRAF is a crucial mediator of resistance to RAF/MEK inhibition in BRAF-mutant melanoma and colorectal cancer models, through sustained ERK pathway activation." (PMID 41023593, 2025). "Pharmacological inhibition of mutant BRAF or MEK1/2 substantially improved the clinical outcomes of melanoma patients, although drug resistance is almost inevitable." (PMID 39970778, 2025). "Melanoma is primarily driven by mutations in proteins of the MAPK pathway, such as BRAF, NRAS, NF1, or the RTK cKIT." (PMID 40943167, 2025). "From the series of melanomas in the present study, one patient with a BRAF-mutant melanoma developed lymphatic and hepatic metastasis two years after the initial diagnosis." (PMID 41010758, 2025). "A wide range of cAEs, occurring at different frequencies, have been reported in registration studies with BRAF/MEKi combinations in melanoma." (PMID 40507236, 2025). "Further, individuals with melanoma and Class I mutations experience better survival with frontline ICI-based therapy than anti-BRAF/MEK therapy, raising questions about the optimal treatment sequencing in NSCLC." (PMID 41450930, 2025). "BRAF-mutant melanoma with resistance to targeted therapies is characterized by increased reliance on OXPHOS, glutamine metabolism, and serine metabolism, which is partially driven by PGC1α." (PMID 40617808, 2025). "Palbociclib has been demonstrated to enhance the therapeutic efficacy of vermurafenib and trametinib in BRAF-mutant melanoma cells." (PMID 39948552, 2025). "Targeting oncogenic drivers in melanoma, the combination of atezolizumab with cobimetinib (anti-MEK) and vemurafenib (anti-BRAF) has been approved for BRAF-V600E-mutant melanoma." (PMID 40950404, 2025). "Eligible studies included clinical trials, observational cohorts, and translational research evaluating biomarkers or toxicity profiles in melanoma patients receiving immune checkpoint inhibitors or BRAF/MEK inhibitors." (PMID 41374434, 2025). "More recent data support the activity of cobimetinib plus vemurafenib in an agnostic fashion showing promising ORR (57%) in solid tumours (n = 31) with BRAF V600E mutations; however EMA marketing authorisation is currently available only for melanoma." (PMID 40093395, 2025). "AR inhibitors, such as AZD3514, ARCC4, and enzalutamide, decrease EGFR and SERPINE1 expression and reduce tumorigenicity in BRAF inhibitor-resistant melanoma cells." (PMID 40940929, 2025). "A 71-year-old male with malignant melanoma (BRAF wild-type) initially received one cycle of adjuvant pembrolizumab, followed by four cycles of ipilimumab/nivolumab after the occurrence of lung metastases." (PMID 40751168, 2025). "In BRAF-mutant melanoma, DTP cells emerging after MAPK inhibitor treatment demonstrate increased intracellular calcium signaling via P2X7-mediated ERK reactivation, which supports survival in the drug-tolerant idling state." (PMID 40894234, 2025). "The emergence of resistance to mutant BRAF-specific inhibitors (BRAFi) requires novel strategies for melanoma treatment." (PMID 41332139, 2025).
melanoma (continued). "The identification of BRAF mutations has led to the development of targeted therapies, such as vemurafenib and dabrafenib, which have shown significant clinical benefits in BRAF-mutant melanoma and other cancers." (PMID 40227591, 2025). "The combination of proteasome and Kv1.3 channel inhibitors results in synergistic effects and prevents the outgrowth of both drug-resistant and -sensitive BRAF-mutant melanoma cells." (PMID 39744692, 2025). "Melanoma is, perhaps, the most recognizable success of BRAF inhibition, with randomized clinical trials comparing BRAF and MEK inhibition to previous generation cytotoxic and small molecule inhibitor agents." (PMID 39976897, 2025). "In melanoma, long-term BRAF inhibitor treatment or acquired resistance increased sensitivity to ferroptosis, as seen with erastin and RSL3 treatments." (PMID 41030783, 2025). "Its potential for monitoring BRAF-mutant melanoma patients’ responses to BRAF/MEKi and detecting resistance mechanisms has been extensively studied." (PMID 39859576, 2025). "In melanoma, the IMspire150 trial of lead-in BRAF and MEKi with vemurafenib and cobimetinib combined with PD-L1 blockade with atezolizumab met its primary end point of improved PFS." (PMID 40486486, 2025). "The overexpression of MMP-1 in melanoma cells is driven by constitutive activation of the ERK pathway, attributed to BRAF mutation and autocrine fibroblast growth factor signaling." (PMID 40574005, 2025). "The phase II single-arm REDUCTOR trial assessed the feasibility of cytoreduction with neoadjuvant BRAF/MEK-inhibitor to facilitate surgical resection of locally advanced, unresectable BRAF-mutant melanoma." (PMID 40857557, 2025). "Recently, mTORC1 activation has been reported as a resistance mechanism in BRAF-mutant melanoma, and combining BRAF/MEKi with the mTORC1 inhibitor rapamycin was shown to effectively target resistant melanoma cells." (PMID 41550951, 2025). "This metabolic flexibility not only supports melanoma growth and progression but also promotes the development of resistance to BRAF/MEK inhibitors." (PMID 40652057, 2025). "This and BRAF [L505H] have been reported in a small number of tumor entities including melanoma, prostate, and pancreatic cancer in cbioportal." (PMID 39876058, 2025). "Genetic mutations, such as those in the BRAF and NRAS genes, are implicated in melanoma pathogenesis." (PMID 41394861, 2025). "Skin melanomas showed a higher frequency of specific gene alterations such as CDKN2A deletion (P < .05), BRAF single-nucleotide variants (SNVs; P < .01), and TERT promoter variants (P < .01) than mucosal melanomas." (PMID 39823560, 2025). "SIRT7 expression also upregulated ERK signaling in BRAF-mutant A375 melanoma cells under stress, which ensured cell survival." (PMID 39935431, 2025). "When melanoma cells are treated with the BRAF inhibitor vemurafenib for a long time, FAO is up-regulated, which contributes to the resistance of melanoma cells to vemurafenib." (PMID 40514365, 2025). "Acquired resistance of BRAF-mutant melanoma cells to vemurafenib and PLX4720 was accompanied by ERK1/2 reactivation followed by repression of the pro-apoptotic proteins BIM-XL and Bmf." (PMID 39935431, 2025). "The first FDA approval of MEK inhibitors came in 2013 with trametinib used for the treatment of unresectable or metastatic BRAF-mutant melanoma." (PMID 41294711, 2025). "In conclusion, our study uncovers the critical role of the SPACA6-hosted miR-99b~125a~let-7e cluster in sustaining BRAF/MEKi resistance in melanoma." (PMID 41550951, 2025). "While BRAF and MEK inhibitors have shown promise for patients with BRAF-mutated melanoma, melanoma’s propensity for developing resistance to therapies complicates treatment regimens, especially in advanced stages of the disease." (PMID 41315179, 2025).
melanoma (continued). "CDK2 induces resistance to BRAF and hsp90 inhibitors and a high ratio of CDK1 expression leads to resistance of melanoma patients to therapeutic agents which causes a significant decrease in OS." (PMID 39820173, 2025). "A trial patient, who had stage 4 V600E BRAF-mutant melanoma and received ipilimumab and nivolumab as ICI therapy." (PMID 40506699, 2025). "The emergence of immunotherapy with immune checkpoint inhibitors and targeted therapy (BRAF/MEK inhibitors) significantly improved melanoma prognosis." (PMID 40507314, 2025). "Similar to the increase of FRA1 in melanoma cells compared to wildtype or BRAF-mutant melanocytes, AXL, CDK6, and Fascin levels are increased in melanoma cells, especially in cells exhibiting high levels of FRA1." (PMID 41286309, 2025). "As a result, it was suggested that MAPK pathway inhibition can alter the immune profile of BRAFV600E melanoma cells, potentially informing combination therapies with BRAF/MEK inhibitors and immunotherapy." (PMID 40636453, 2025). "Studies have reported upregulation of ID3 (inhibitor of differentiation 3, a helix-loop-helix TF superfamily member) in melanomas of patients treated with a BRAF inhibitor, and silencing ID3 resulted in enhanced sensitization of melanoma to vemurafenib." (PMID 40558548, 2025). "Here, we uncovered a role for SPACA6-hosted miR99b~125a~let-7e cluster in sustaining BRAF/MEKi resistance in melanoma tumors and cell lines." (PMID 41550951, 2025). "The BRAF protein, a MAPK pathway member, is the most commonly mutated in melanoma, with the V600E mutation occurring in about 50% of cases." (PMID 41199020, 2025). "In recent studies, MIA has also been evaluated as a dynamic marker for treatment monitoring, particularly in the context of BRAF-mutant melanoma." (PMID 40981345, 2025). "In this study, we report for the first time that the SPACA6-hosted miR-99b~125a~let-7e cluster contributes to melanoma cell and tumor resistance to BRAF/MEKi through a mechanism involving the mTOR signaling pathway." (PMID 41550951, 2025). "Several studies have shown that monitoring the levels of BRAF mutation ctDNA can be a useful tool for assessing the response to BRAF +/− MEKi in patients with BRAF V600-mutant melanoma." (PMID 39859576, 2025). "Given that the MAPK pathway is frequently activated in melanoma through mutations in BRAF, combining CDK4/6is with BRAF inhibitors (BRAFis) and MEK inhibitors (MEKis) offered a promising therapeutic strategy." (PMID 40282469, 2025). "Meanwhile, the combination of TAE684 and vemurafenib exhibits a synergistic effect, offering insights into sensitizing melanoma to BRAF-targeted therapy." (PMID 41198656, 2025). "BRAF inhibitors are currently approved for the treatment of several other malignancies including melanoma and non-small cell lung carcinoma." (PMID 40826136, 2025). "Las mutaciones BRAF de clase I, específicamente BRAF V600E, tienen una alta frecuencia en tumores como el melanoma, cáncer colorrectal y cáncer de tiroides." (PMID 40977817, 2025). "Mutations in the oncogenes BRAF and MEK are commonly observed in melanoma, leading to the hyperactivation of the MAPK signaling cascade." (PMID 40331942, 2025). "This approach identified mRNA transport and translation pathways as key regulators of the metabolic response to BRAFi in BRAF V600E melanoma cells." (PMID 40872623, 2025). "AR42 plus pazopanib also distinctly prolonged the survival of mice with BRAF/MEK inhibitor-resistant melanoma." (PMID 39935431, 2025). "Notable findings include NRAS Q61L melanomas being enriched for modules involving C19orf10 and ARF4, while BRAF V600E melanomas were enriched for modules involving ALAS1 and MYO1B." (PMID 39796775, 2025). "Crucially, they found that treating melanoma cells with a BRAF inhibitor induces Jun, which coincides with an epithelial–mesenchymal transition." (PMID 39859271, 2025).